TYMS (thymidylate synthetase)
Diseases named in the same sentence as TYMS in open-access papers (continued):
Sharing a sentence is not in itself a finding about the gene and the disease.
tumor (continued). "Furthermore, high TYMS levels are associated with poor overall and shortened recurrence-free survival, indicating their importance to tumour subsistence and metastasis." (PMID 39518122, 2024). "Importantly, we observed that TYMS cooperates with heterozygote Ink4a/Arf inactivation increasing the underlying tumor incidence and decreasing survival of hTS/Ink4a/Arf+/- mice that otherwise show indolent tumors with a long latency." (PMID 37106126, 2023). "We first examined whether high TYMS levels would cause DNA double strand breaks (DSB) in primary tumor cell lines derived from hTS/Ink4a/Arf−/− and Ink4a/Arf−/− mice." (PMID 37106126, 2023). "Therefore, TYMS abnormal expression is associated with a variety of tumors and is frequently used as a target for anti-tumor drugs, including 5-FU." (PMID 35093082, 2022). "In addition, resistance to platinum doublets of chemotherapy was found to be greatly increased in patients with a KRAS mutation and low expression of the BRCA1 and TYMS genes in tumor tissue." (PMID 36294786, 2022). "The increase in tumor growth was associated with a significant increase in TYMS activity." (PMID 36612253, 2022). "The results showed that the expression of TYMS was negatively correlated with tumor mutational burden and microsatellite instability, and positively correlated with the expression of four methyltransferases (DNMT1: red, DNMT2: blue, Dnmt3A: green and DNMT3B: purple)." (PMID 35003215, 2021). "In addition, we also analyzed the relationships between TYMS expression and immune neoantigens, tumor mutational burden, microsatellite instability and methylase expression." (PMID 35003215, 2021). "Given that TYMS is a chemotherapy target, an rs495139-associated increase in ENOSF1 and decrease in TYMS expression might suggest a favorable tumor profile for patient survival." (PMID 30134598, 2018). "The biomarkers profile was generally IHC-based in this cohort, and as such drew on evidence from previous studies that associated levels of key proteins in the tumor with responses to particular classes of cytotoxics, e.g. thymidylate synthetase levels with fluorouracil (5FU) response." (PMID 29560111, 2018). "TYMS is associated with aggressive tumor features and early PSA recurrence in PCa45." (PMID 26924343, 2016). "Notably, most of them suggest that elevated levels of TYMS expression are significantly associated with reduced tumor responses and shorter survival rates." (PMID 26502926, 2015). "High TYMS expression levels were associated with unfavorable tumor phenotype." (PMID 25762627, 2015). "ABCC3, RFC‐1, PCFT, MFT, MTHFD2, and TYMS expression was determined by qPCR and related to tumor response and 3‐year progression‐free survival (PFS)." (PMID 40357991, 2025). "Mice injected with SW480 cells overexpressing TYMS exhibited accelerated malignant tumor formation compared to control groups." (PMID 39744483, 2025). "In the clinical-pathological correlation analysis, a correlation was found between TYMS and tumor size as well as tumor N staging." (PMID 39744483, 2025). "The decrease in phosphorylation impaired HNF4A’s ability to regulate the transcription of TYMS, which in turn inhibited TYMS expression and enhanced the anti-tumor effects of 5-FU." (PMID 41326348, 2025). "Subsequently, we assessed the influence of TYMS on tumor formation ability through a xenograft mouse model." (PMID 39744483, 2025). "Impaired TYMS activity or altered affinity for antifolate drugs such as MTX contributes greatly to tumour cell resistance to these treatments." (PMID 40270992, 2025). "The immunohistochemical staining demonstrated TYMS expression in tumor tissues was markedly higher than adjacent tissues, aligning with the conclusions drawn from the database analysis." (PMID 39744483, 2025). "The increased expression of TYMS in CRC tissue implied that TYMS plays a role in influencing the biological behavior of the tumor." (PMID 39744483, 2025).
tumor (continued). "Histopathological examination (HE) along with immunohistochemistry assays were conducted on isolated tumor tissues focusing on TYMS and PTGS2 expression." (PMID 39744483, 2025). "In patients treated with 5-FU, chemoresistance is described to be generated secondary to selective pressure, where tumor clones are selected when TYMS has greater activity." (PMID 39940936, 2025). "Patients who experienced recurrence within 5 years of follow-up had a lower expression of TYMS (p < 0.001) in tumor tissue compared to mucosa." (PMID 39998667, 2025). "The results revealed that compared to HMCB with MTHFD2-OE or TYMS-OE, PRKDC-OE cells that overexpressed with MTHFD2 or TYMS showed significantly elevated tumor cell proliferation." (PMID 39039072, 2024). "Thymidylate synthase (TYMS) has been spotlighted as an essential target for tumor chemotherapeutic agents." (PMID 39353904, 2024). "TYMS is an essential target of 5-FU and some folate analogs, and its expression correlates with tumor chemoresistance." (PMID 39353904, 2024). "Understanding the regulatory mechanisms of TYMS and its interactions with other factors contributes to a deeper understanding of tumor biology." (PMID 39353904, 2024). "In this report we show that TYMS overexpression in Ink4a/Arf null background accelerates tumor progression, enhances tumor metastases, decreases overall survival and induces DNA damage and genomic instability." (PMID 37106126, 2023). "The MTT assay, colony formation assay, and nude mouse subcutaneous tumor model found that the overexpression of TYMS increased cell proliferation." (PMID 37682862, 2023). "The results revealed that AURKA, BIRC5, CCNB1, CDK1, CDKN3 and TYMS were significantly upregulated in tumor tissues." (PMID 37393234, 2023). "The effect of TYMS on tumorigenesis in vivo was evaluated by xenograft mouse model, and the tumor volumes and weight in TYMS-overexpression cells were significantly increased compared to that in the control group." (PMID 37682862, 2023). "We next tested if TYMS overexpression plays a role in tumor development in homozygous Ink4a/Arf−/− mice." (PMID 37106126, 2023). "We also show that TYMS inhibition in vitro reduces cell proliferation and sensitizes tumor cells to antimetabolite chemotherapy currently used in clinic." (PMID 37106126, 2023). "Our data shows that activation of TYMS in Ink4a/Arf null background enhances uncontrolled cell proliferation and tumor growth, supporting the development of new agents and strategies targeting TYMS to delay tumorigenesis and prolong survival." (PMID 37106126, 2023). "We previously show that ectopic expression of human thymidylate synthase (hTS or TYMS) can directly participate in tumorigenesis of murine cells resulting in tumor formation in nude mice." (PMID 37106126, 2023). "Although TYMS has been studied for many years as a tumor prognostic marker and therapeutic target, we previously reported that ectopic overexpression of human TYMS (also designated hTS) can transform cells in vitro and result in tumor formation in nude mice." (PMID 37106126, 2023). "Downregulation of TYMS in vitro decreased cell proliferation and sensitized tumor cells to antimetabolite chemotherapy." (PMID 37106126, 2023). "A role for deregulated TYMS to enhance cell proliferation of cells derived from hTS/Ink4a/Arf−/− tumor was further tested by downregulating TYMS protein using shRNA." (PMID 37106126, 2023). "Our data now show that loss of Ink4a/Arf concurrent with ectopic TYMS expression further increases the number of cells in S-phase and DNA DSB in hTS/Ink4a/Arf−/− tumor-derived cells." (PMID 37106126, 2023). "In summary, these data show that downregulation of TYMS expression with shRNA inhibits hematopoietic tumor growth in vivo and suggests that lowering TYMS levels enhanced tumor cell inhibition in vitro by pemetrexed or gemcitabine treatment." (PMID 37106126, 2023).
tumor (continued). "In summary, both human and mice data support deregulated TYMS as an oncogenic stimulus that concurrent with Ink4a/Arf inactivation accelerates tumor progression and decreases survival." (PMID 37106126, 2023). "In PCa, the overexpression of TYMS exhibits a close correlation with unfavorable tumor phenotype and early PSA recurrence." (PMID 36034466, 2022). "Studies have shown the downregulation of TYMS contributes to 5-FU sensitivity, while the overexpression of TS represents a pathway of tumor cells resistance to 5-FU." (PMID 35743738, 2022). "The conjugate enters cells through folate-binding protein, which is overexpressed on the plasma membrane of tumor cells and targets the contact area of two TYMS subunits shifting the monomer-dimer equilibrium towards the formation of inactive monomers." (PMID 35053254, 2022). "Recently, the expression of genes such as TYMS, RRM1, TUBβ3, and EGFR was found to be associated with tumor histological type (at p < 0.05) and progression-free survival rates." (PMID 36294786, 2022). "Comparing with peri-tumor controls, the expression of TYMS was significantly increased in HCC tissues which were consistent with the bioinformatics results obtained by the TCGA dataset." (PMID 34858842, 2021). "The gene expression profiling also proved that TYMS is up-regulated in metastatic tumor tissues from GSE27635, which contained 24 pairs of intratumoral and peritumoral tissue from HCC patients with bone metastases." (PMID 34858842, 2021). "Detection of the TYMS expression in tumor cells is expected to make an early diagnosis of HCC metastasis." (PMID 34858842, 2021). "TYMS is one of the most relevant targets for anti-tumor therapy, a lot of work has been done on TYMS as an anti-tumor target and drug resistance in the past." (PMID 34858842, 2021). "The expression level of TYMS was negatively correlated with microsatellite instability (MSI) and Tumor mutation burden (TMB), and positively correlated with methylase expression in DNMT1, DNMT2, DNMT3A and DNMT3B." (PMID 35003215, 2021). "Since only patients with low expression of TYMS can respond to 5-FU, individualized chemotherapy regimens can be selected according to the expression of TYMS and tumor classification." (PMID 33858449, 2021). "Being a fluorinated analog of uracil, 5-FU exerts its cytotoxic effects through the inhibition of thymidylate synthase (TYMS) that subsequently impairs cellular DNA synthesis functions in tumor cells." (PMID 34571731, 2021). "Colony formation assays found silencing of TYMS expression displayed significant differences in colony formation comparing with the control, indicating that TYMS affects tumor growth." (PMID 34858842, 2021). "Patients with younger age (P = 5.00 × 10-3) and advanced tumor stage (P < 1.00 × 10-4) were prone to have decreased expression of TYMS in our investigation." (PMID 33046972, 2020). "The upregulation of HSP90 activates Src and upregulates the Src downstream target thymidylate synthase (TYMS), which subsequently increases tumor growth in vivo." (PMID 32456226, 2020). "Patients with tumours expressing high levels of TYMS have a poorer OS (overall survival) compared with those with tumours expressing low levels of TYMS9,10." (PMID 30728402, 2019). "When expression of this family of miRNAs is restored in these malignancies, the miRNAs act as tumor supressors repressing the oncogenes TYMS, ZEB2, and MDM223,28,29." (PMID 30038317, 2018). "5-FU is further activated in the tumor to cytotoxic compound FdUMP that inhibits DNA synthesis by competing with nucleotide precursor for binding with thymidylate synthase (TYMS)." (PMID 29088787, 2017). "The expression levels of four genes (HIF1A, MTHFD1, GGH and TYMS) in tumor tissue before CRT can predict the response to preoperative CRT including S-1 or UFT/LV." (PMID 28417167, 2017).
tumor (continued). "The expression levels of four genes, HIF1A, MTHFD1, GGH and TYMS, in tumor tissues can predict the response to preoperative CRT including either S-1 or UFT/LV." (PMID 28417167, 2017). "Tumor cells with higher TYMS expression exhibited higher proliferative and metastatic activities due to its accelerated effect on the DNA replication." (PMID 28056823, 2017). "Expression of FOLR1, FPGS, MLH1 and TYMS (each p<0.0001) differed significantly between all four tumor types." (PMID 27064343, 2016). "High activity of TYMS activity and GPI1 expression was associated with poor prognosis of patients with NSCLC, as was increased activity of LDH with tumor stage." (PMID 27602772, 2016). "The purpose of this study was to quantitatively assess the impact of TYMS gene expression in tumor cells as a predictor of the efficacy of pemetrexed therapy in patients with advanced non-small cell lung cancer (NSCLC) treated at our institution." (PMID 26502926, 2015). "TYMS expression was unrelated to PTEN deletions (p = 0.9535) but tightly linked to high Gleason grade, advanced pathological tumor stage and early PSA recurrence (p < 0.0001)." (PMID 25762627, 2015). "As part of the drug's rationally designed activation, 5-FU is further activated in the tumour to cytotoxic compounds that inhibit DNA synthesis by competing with nucleotide precursors for binding with thymidylate synthase (TYMS)." (PMID 24647007, 2015). "On entering the tumor cell, 5-FU can exert cytotoxic effects via the inhibition of thymidylate synthetase (TS) or through incorporation into RNA and DNA, which lead to the activation of apoptosis." (PMID 25503826, 2015). "For additional non-TYMS genes analyzed, XRCC1 (c.1196G>A, rs25487) and MDR1 (c.3435C>T, rs1045642) showed a potential association to tumor response." (PMID 25232828, 2014). "By contrast, another study conducted on Japanese patients demonstrated that tumor cells with higher TYMS expression exhibit higher proliferative activity in NSCLC, especially adenocarcinoma." (PMID 24649266, 2013). "Five-fluorouracil (5-FU), one of several TYMS inhibitors, is widely used to induce temporary tumor regression and improve survival, especially for gastrointestinal cancers." (PMID 23915286, 2013). "Of note, the reported study also shows that TYMS levels are significantly higher in CIMP-positive tumours with respect to CIMP-negative ones, confirming our results." (PMID 23446022, 2013). "Damage response protein CHK1 changed from almost no detectable staining in the primary biopsy to 50%, nuclear staining of NQO1 increased from 20 to 70% and TYMS staining increased from below 1% to 25% of tumour cells." (PMID 22905093, 2012). "TYMS and UGT1A polymorphisms influence on tumour response and toxicities derived from irinotecan/5FU treatment in CRC patients." (PMID 20628391, 2010). "After normalization to anti-BSA levels, standardized ratios of anti-AGR2, anti-HAPLN1, anti-IGFBP5, and anti-TYMS were significantly higher in malignant and early-stage CMTs, suggesting selective amplification of tumor-specific immune responses despite global immune suppression." (PMID 41562247, 2026). "In the present study, both FPGS and GGH were expressed at higher levels in tumors compared to mucosa, indicating an increased intracellular folate turnover in tumors, a finding further supported by the high expression of the proliferation marker TYMS in tumor tissue." (PMID 39998667, 2025). "In this study, we speculated that in GC, the inhibition of HDAC3 by chidamide might lead to a downregulation of TYMS expression, thereby enhancing the anti-tumor efficacy of 5-FU." (PMID 41326348, 2025). "The aim of the present study was to assess the association between primary tumor expression of six selected folate pathway genes, ABCC3, RFC‐1, PCFT, MFT, MTHFD2, and TYMS, and tumor response as well as 3‐year progression‐free survival (PFS) of patients with mCRC." (PMID 40357991, 2025).
tumor (continued). "Additionally, high TYMS levels can activate the mTOR signaling pathway, further promoting tumor proliferation." (PMID 40496862, 2025). "Moreover, among 100 patients where TYMS protein expression was detectable in both the cancerous and adjacent tissues of the same patient, the upregulation rate of TYMS protein expression in CRC tumor tissues was 60% (60/100)." (PMID 39744483, 2025). "Furthermore, the observed synergistic anti-tumor effect of combining the ferroptosis inducer erastin with the TYMS inhibitor 5-FU provided valuable insights for multi-targeted chemotherapy." (PMID 39744483, 2025). "Furthermore, the in vivo decrease of TYMS expression lowered tumor occurrence, slowed tumor progression, and extended survival time in mice." (PMID 39353904, 2024). "MiR-330-5p and miR-140-3p inhibited tumor proliferation by suppressing TYMS expression." (PMID 39353904, 2024). "Since loss of INK4A/ARF expression is one of the most common somatic events in human tumors and is associated with elevated TYMS levels, we reasoned that activated TYMS may cooperate with INK4a/ARF loss to promote tumor growth." (PMID 37106126, 2023). "In addition, we show that activated TYMS promotes tumor growth and metastases in homozygote hTS/Ink4a/Arf−/− GEMM and can enhance DNA damage and genomic instability in tumor cells derived from hTS/Ink4a/Arf−/− mice." (PMID 37106126, 2023). "In contrast, when spleens were enlarged, we did not observe a significant difference in the proportion of cells in S-phase between hTS/Ink4a/Arf−/− and Ink4a/Arf−/− mice (28.86% vs 30.44%, n = 2 and 3, respectively), indicating that TYMS accelerates early tumor progression." (PMID 37106126, 2023). "To investigate if TYMS overexpression was involved in accelerating tumor growth by altering the deregulated cell cycle kinetics, we measured DNA content and incorporation of the thymidine analog bromodeoxyuridine (BrdU) into splenic cells of 5.9-month-old mice in vivo." (PMID 37106126, 2023). "In addition, TYMS inhibition sensitized tumor cells derived from hTS/Ink4a/Arf−/− mice to pemetrexed and gemcitabine treatment further supporting the clinical impact of regulating TYMS levels." (PMID 37106126, 2023). "Moreover, high expression of TYMS in tumor tissues indicates poor responsiveness to 5-FU, and thereby worse overall prognosis." (PMID 36759799, 2023). "Also, miR-215 is involved in the cellular 5-FU response via regulation of the TYMS expression in tumor cells." (PMID 36759799, 2023). "In addition, we showed that ectopic TYMS markedly increased tumor growth and metastasis in hTS/Ink4a/Arf−/− mice." (PMID 37106126, 2023). "To test this hypothesis, we have now studied the ability of ectopic TYMS to cooperate with Ink4a/Arf deletion in a defined mouse tumor model to promote tumorigenesis." (PMID 37106126, 2023). "To directly test if high TYMS levels is responsible for the increased tumor proliferation in hTS/Ink4a/Arf−/− mice, we asked whether TYMS downregulation would result in decreased cell proliferation." (PMID 37106126, 2023). "In addition, quantitative RT-PCR for TYMS demonstrated a 300 to 9000-fold upregulation of TYMS expression in spleen and lymph nodes isolated from hTS/Ink4a/Arf−/− as compared to Ink4a/Arf−/− tumor bearing mice (P < 0.05)." (PMID 37106126, 2023). "TYMS is used as the target of anti-tumor drugs 5-fluorouracil to inhibit tumor cells proliferation." (PMID 37682862, 2023). "Moreover, several genes from the G2M downregulated gene set, including MKI67, MCM2, CCND1, and their STRING-interacting genes MECOM, TYMS, and MTHFR, are associated with neoplasms." (PMID 37958729, 2023). "In addition, depletion of TYMS in vivo by TYMS shRNA reduced tumor incidence, delayed tumor progression and prolonged survival in hTS/Ink4a/Arf−/− mice." (PMID 37106126, 2023). "Therefore, inhibition of TYMS is an attractive target for intervention, especially given the spectrum of common adult tumor types that would benefit from TYMS inhibition." (PMID 37097751, 2023).